GSK3B (glycogen synthase kinase 3 beta)
Diseases named in the same sentence as GSK3B in open-access papers (continued):
Sharing a sentence is not in itself a finding about the gene and the disease.
tumor (continued). "Knocking down of GSK3β in MG63 cells did not significantly affect the total FAK in mRNA and protein, but reduced the p-FAKY397, suggesting an involvement in the mechanism of GSK3β-mediated tumor metastasis." (PMID 33969873, 2021). "GSK-3β is particularly important in tumor progression and modulation of oncogenes (including beta-catenin, cyclin D1, and c-Myc) because it acts as a part of the destruction complex of β-catenin in the Wnt/β-catenin pathway." (PMID 34955846, 2021). "GSK3β-specific inhibitors and small interfering (si)RNA-mediated knockdown of GSK3β attenuated tumor cell survival and proliferation, while inducing apoptosis in ESCC cells and their xenograft tumors in mice." (PMID 32678196, 2020). "Our in vitro experiments demonstrated that GPNCA silencing inhibited tumor growth via inhibiting its nearby gene GSK3B." (PMID 32029792, 2020). "Expression of the canonical skeletal muscle WNT agonist Wnt5a (WNT5A), canonical WNT receptor Fzd1 (FZD1), and β‐catenin itself (CTNNB1) was all reduced with C‐26 tumor burden, whereas the negative regulator of β‐catenin, GSK3B, was up‐regulated." (PMID 31930715, 2020). "Consistent with the in vitro experiments, the expression levels of RHBDD1, Wnt1, β-catenin and p-GSK-3β were down-regulated in the tumor xenografts of mice in the miR-924 mimic group compared with miR-NC group." (PMID 33041671, 2020). "Here, we found GPNCA was a typical divergent lncRNA to GSK3B, whose overexpression promoted tumor growth in many cancers." (PMID 32029792, 2020). "It downregulates the CTHRC1-mediated GSK-3β/β-catenin signal and inhibits tumor cell proliferation, invasion, and migration." (PMID 32848510, 2020). "Although this was shown with one inhibitor only, results are intriguing as they point out a possible immunosuppressive effect of GSK3β inhibitors in the tumor microenvironment." (PMID 32850361, 2020). "Here, we review the possible role of GSK3β in the immune tumor microenvironment, with goal to guide future research that tests GSK3β inhibition as an immunotherapy adjunct." (PMID 32850361, 2020). "In order to further explore the targeted drugs of the GSK3B gene in GI cancer, we divided the tumor samples into two groups based on the median GSK3B expression level for differential expression analysis." (PMID 33365328, 2020). "Similar to ESCC cell cultures, the GSK3β inhibitors significantly reduced tumor cell proliferation (Ki-67-positive cells), pGSS641 level and cyclin D1 expression, while inducing apoptosis (TUNEL- and c-PARP-positive cells)." (PMID 32678196, 2020). "It is assumed that Wnt signaling promotes tumor cell proliferation, inhibits differentiation, and mediates endothelial function by connecting GSK-3β, β-catenin, E-cadherin, APC, and Norrin29." (PMID 32587771, 2020). "In this scenario, GSK-3β was serving as a tumor promoter as inhibition of its activity suppressed growth." (PMID 32365809, 2020). "In Wilms3 the tumor carried a p.T41A CTNNB1, an amino acid that is also a target for phosphorylation by GSK3β, and the Wilms11 tumor carried a p.S45F mutation." (PMID 33379206, 2020). "These morphological changes in tumor cells induced by GSK3β inhibition coincided with the disruption of pathways that are mediated sequentially by focal adhesion kinase (FAK), guanine nucleotide exchange factors (GEFs), Rac1 and c-Jun N-terminal kinase (JNK)." (PMID 32503133, 2020). "9-cis-RA was alone inefficient to improve the anti-tumor effect of sorafenib when GSK-3β remained active." (PMID 31938062, 2020). "Collectively, these data illustrate the multifaceted effects of GSK3β on the immune system as potentially both promoting and suppressing aspects of anti-tumor immunity." (PMID 32850361, 2020). "Together, these studies provide evidence that GSK3β enhances the process of tumor invasion and probably also that of metastatic spread." (PMID 32503133, 2020). "We found that sorafenib can extensively activate GSK-3β both in vitro 32 and in tumor microenvironment." (PMID 31938062, 2020).
tumor (continued). "A growing body of literature supports a multifaceted role for GSK3β in the immune tumor microenvironment." (PMID 32850361, 2020). "Evidences suggested that both downregulated expression and inhibited kinase activity of ILK lead to attenuated phosphorylation of Ser473 and GSK-3β, resulting suppressed tumor growth and metastasis 14, 23-27." (PMID 31897228, 2020). "For example, regulatory targets of hsa-miR-3065-3p, such as GSK3B (Glycogen Synthase Kinase-3), are involved in apoptosis, cell cycle, DNA repair, tumor growth, invasion, and metastasis pathways." (PMID 32704070, 2020). "Other studies have shown that glycogen synthase kinase-3β (GSK-3β) can promote the degradation of β-catenin, while inhibition of GSK-3β has been proven to induce β-catenin signaling pathway activation in various tumor models." (PMID 32904598, 2020). "In light of this, we previously reviewed the pivotal role of GSK3β as a hub that tightly connects the pathways and cellular events responsible for tumor invasion and resistance to therapy." (PMID 32503133, 2020). "Following GSK3β inhibition these cells dedifferentiate into pluripotent memory stem T-cells with anti-tumor capacity via activation of the Wnt/β-catenin pathway." (PMID 32503133, 2020). "There are several mutations that can cause an accumulation of β-Catenin in tumor cells such as mutations of the APC gene, point mutations in GSK-3β or mutations in β-Catenin gene itself." (PMID 32811441, 2020). "GSK-3β is a tumor promoter, and protein crosstalk between Wnt and NF-κB positively regulates NF-κB activity and confers selective growth of CRC cells." (PMID 32587771, 2020). "Therefore, targeting of GSK3β in musculoskeletal tumors may have three advantages: direct therapeutic effect against the tumor, reduction of normal tissue defect caused by surgical removal of the tumor, and enhancement of adjacent normal tissue preservation." (PMID 32503133, 2020). "In vivo, the ectopic tumor volume and weight were significantly reduced in LV-AQP9 group compared with the control, and the levels of DVL2, GSK-3β, CyclinD1 and β-catenin were down-regulated in tumor tissues." (PMID 31969493, 2020). "In summary, GSK3β contributes to tumor cell survival and proliferation by interacting with distinct pro-oncogenic pathways, the cell cycle pathway, the mitotic process and probably also aberrant glycolysis." (PMID 32503133, 2020). "To verify the tumor-suppressive function of GSK3β, we performed TOP/FOP luciferase reporter assays and found that silencing GSK3β antagonized the suppressive effects of MYH9 knockdown on Wnt signaling." (PMID 32296025, 2020). "The isobavachalcone, a flavonoid extracted from Psoralea corylifolia, also inhibits growth and colony formation of CRC tumor cells as well as the induction of apoptosis through the inhibition of the AKT/GSK3β/β-catenin pathway have been noted." (PMID 33276489, 2020). "Cell proliferation pathways mediated by c-Myc, cyclin D1 and STAT3 can promote unrestrained GSK3β-dependent tumor cell proliferation." (PMID 32503133, 2020). "To investigate the mechanism by which GSK3β sustains tumor cell survival and proliferation, we examined the effect of GSK3β inhibition on the cell cycle profile in ESCC cells." (PMID 32678196, 2020). "Immunohistochemistry (IHC) staining of xenograft tumor sections demonstrated that the upregulation of miR-4721 reduced the expression of GSK3β, which confirmed our deduction." (PMID 33230457, 2020). "Further, WDR41 demethylation or up‐regulation suppressed the proliferative, migratory and tumour formation abilities of MDA‐MB‐231 cells by negatively regulating the AKT/GSK‐3β/β‐catenin signalling pathway, and this effect was attenuated by knockdown of WDR41." (PMID 32394588, 2020). "ESCC is the 6th leading cause of cancer-related mortality worldwide and the dismal outlook of this disease has led us to investigate the putative tumor-promoting role of GSK3β as a new therapeutic target in ESCC." (PMID 32678196, 2020).
tumor (continued). "The reduction of Mcl-1 protein by GSK3β- β-TrCP axis-mediated Mcl-1 ubiquitination and degradation enhances tumor-killing efficacy of chemotherapy agents." (PMID 32276600, 2020). "Similar trends were observed for the levels of GSK3β mRNA in normal and tumor tissues of ESCC patients referenced from the TCGA database." (PMID 32678196, 2020). "Several previous studies on the tumor-suppressive roles of GSK3β in various oncogenic pathways showed that it was inactivated mostly through S9 phosphorylation." (PMID 32678196, 2020). "Our study further showed that overexpression of GSK-3β conferred HCC cell proliferation, colony formation and tumor development, while targeting GSK-3β by tideglusib can significantly induce about 22.3% of growth inhibition in HepG2/3β xenografts." (PMID 31938062, 2020). "Concordant with the putative bipolarity of GSK-3β in tumor biology, results on the transcriptional profile of various EMT related genes in response to SB216763 were summarized as a dysregulated EMT without any clear direction by the authors of this study." (PMID 32681294, 2020). "In embryonal rhabdomyosarcoma, inhibition of GSK3β activates the canonical Wnt pathway by stabilizing β-catenin, leading to reduced tumor proliferation and differentiation of tumor stem-like cells and a reduction in their self-renewal capacity." (PMID 32503133, 2020). "Higher levels of GSK3B are often observed in tumor tissues and overexpression of GSK3B can enhance tumorigenicity." (PMID 32164570, 2020). "In contrast, many previous studies have demonstrated direct tumor-promoting roles of GSK3β in at least 25 different cancer types (reviewed in Ref.23)." (PMID 32678196, 2020). "Several tumor studies describe that Relaxin promotes matrix invasion by affecting the Wnt/β-Catenin and GSK3β pathway 57-59." (PMID 32226528, 2020). "Conversely, depletion of β-catenin prevented miR-26a-induced tumor growth suggesting that miR-26a promotes CCA growth by inhibition of GSK-3β and subsequent activation of β-catenin." (PMID 32140709, 2020). "On the other hand, previous findings have indicated GSK-3β as a tumour suppressor in breast cancer because it increases the sensitivity of chemotherapy and inhibits PI3K/Akt and Wnt signalling, thus playing a key role in the cell cycle and survival." (PMID 32211045, 2020). "In summary, the evidence described in this section places GSK3β at the center of a trigonal intersection between the biological hallmarks of cancer, notably tumor cell survival and proliferation, invasion, resistance to therapy and CSC phenotype." (PMID 32503133, 2020). "Sustained activity of human telomerase reverse transcriptase (hTERT) and telomerase in response to aberrant GSK3β contributes to the immortalization of tumor cells from the colon and rectum, pancreas, liver, lung, urinary bladder, ovary and uterine cervix." (PMID 32503133, 2020). "Our previous study showed that sCLU acted as a regulator of AKT/GSK-3β signaling, thereby directing chemoresistance and tumor growth of HCC cells." (PMID 32059741, 2020). "The transcriptome data of GI cancer were integrated, and tumor samples were divided into the high and low expression groups according to the median level of the GSK3B gene expression." (PMID 33365328, 2020). "Inactivation of GSK-3β by tideglusib can potentiate 9-cis-RA enhancement of sorafenib sensitivity (tumor inhibition from 48.3% to 93.4%)." (PMID 31938062, 2020). "Consistent with previous studies by our group and others (reviewed in Refs.18–21,23), inhibition of GSK3β attenuated tumor cell survival and proliferation and induced apoptosis in ESCC cells and in xenograft tumors." (PMID 32678196, 2020). "This review has presented current knowledge regarding the tumor-promoting roles of GSK3β and the therapeutic efficacy of its inhibition." (PMID 32503133, 2020).
tumor (continued). "In MDA-MB-231 xenografts, recombinant as well as adenovirus-mediated adiponectin overexpression, regressed tumor development, inhibited secondary tumor development in adjacent fat pads, and prevented lung metastasis via the GSK3β/βcatenin signaling pathway." (PMID 31121868, 2019). "Altogether, these data indicate that FOXO1 induces GSK3β to reduce β-catenin/TCF4-mediated tumor stemness and EMT signals." (PMID 31754475, 2019). "It is generally believed that GSK3β is a tumor suppressor, and the activity of tumor cells is related to the inhibition of GSK3β, and is also a downstream molecule of PI3K/AKT pathway." (PMID 31533855, 2019). "Of note are the cohorts described by Ma and Richardson in which GSK3β is significantly upregulated in tumor tissue as compared to the normal mammary gland." (PMID 30845991, 2019). "Together with GSK3β, Fbxw7 controls the turnover of a number of key oncogenes such as c-Myc, Cyclin E and NOTCH and has emerged as an important tumour suppressor that is frequently mutated in cancer." (PMID 30854564, 2019). "By western blotting analysis, we found that AF38469 decreased the activation of GSK-3β/β-catenin/twist axis in tumor tissues." (PMID 30814514, 2019). "On the other hand, a tumor-promoting effect of GSK3β has been indicated in colon and pancreatic cancers." (PMID 31744046, 2019). "GSK3β is considered to be a tumor suppressor due to its ability to inhibit the Wnt-β-catenin pathway." (PMID 30845991, 2019). "This study indicated that ERs were likely to promote NSCLC progression by modulating the integrated membrane receptor signaling network composed of EGFR, Notch1 and GSK3β/β-Catenin pathways and then affecting tumor cell behaviors." (PMID 31511014, 2019). "A decrease in immunoreactivity of phospho-GSK3β was also observed in excised tumor tissue from hirsutine-treated animals." (PMID 29789524, 2018). "We identified 18 FIBP-interacting proteins, among which GSK3β was selected for further study because it is widely recognized as a protein upstream of cyclin D1 and is closely related to tumor development." (PMID 30275459, 2018). "Our in vivo study also showed that hirsutine effectively inhibits tumor growth in a A549 xenograft mouse model through ROCK1/PTEN/PI3K/Akt signaling-mediated GSK3β dephosphorylation and apoptosis." (PMID 29789524, 2018). "The phosphorylation of GSK3β decreased in the subcutaneous adenocarcinoma, while it remained unchanged in the primary tumor." (PMID 29415661, 2018). "In a murine xenograft model, Fap1 inhibition was associated with decreased tumor growth, delayed progression after oxaliplatin, decreased relative abundance of CD133+CD44+ cells, and phosphorylation of Fap1 substrates (Fas and Gsk3β)." (PMID 29899829, 2018). "In PaCa, it has been reported that inhibiting GSK3β activity with inhibitors or RNAi can preferentially attenuate the survival and proliferation of tumor cells and induce them to undergo apoptosis." (PMID 29949874, 2018). "Dioscin treatment induced a significant reduction of phosphorylated-Akt (Ser473), phosphorylated-GSK3β (Ser9) and β-catenin in same mice tumor samples." (PMID 29497056, 2018). "Multiple key negative regulators, such as APC, GSK-3β, and Axin, are suppressed in cancer, contributing to the promotion of tumor progression through regulation of the Wnt/β-catenin pathway." (PMID 29304823, 2018). "In NSCLC, GSK3β has been recently reported to be over-expressed in tumor tissue compared to normal tissue and this was found to correlate with poor patient prognosis." (PMID 29789524, 2018). "The Akt/GSK-3β signaling pathway plays an important role in the regulation of EMT in tumor progression." (PMID 30670971, 2018).
tumor (continued). "Glycogen synthesis kinase 3 β (GSK-3β) has complex roles in cell signaling, including a tumor suppressor function through inhibition of the β-catenin complex." (PMID 30279968, 2018). "Together, these results indicate that hirsutine effectively inhibits tumor growth in an A549 xenograft mouse model through ROCK1/PTEN/PI3K/Akt signaling-mediated GSK3β dephosphorylation and apoptosis." (PMID 29789524, 2018). "IB analysis revealed that increased protein expression level of GSK-3β and p-GS in tumor tissues compared with their normal counterparts." (PMID 29445085, 2018). "On one hand, GSK3β can inhibit β-catenin and subsequent tumor progression, and its downstream targets (c-myc, cyclin D1, PPARdelta) are also reported to be involved in this process." (PMID 30275459, 2018). "Although the role of GSK3β is controversial, it is known to act as a tumor suppressor by regulating cell cycle proteins." (PMID 29728077, 2018). "Analysis of GSK3β and S9-GSK3β levels in our tumour panel demonstrated that GSK3β is in active state in the majority of the tumours." (PMID 29724995, 2018). "RKIP dissociation from GSK3β de-represses GSK3β-mediated inhibition of cyclin D stabilization and induction of β-catenin, Snail and Slug, thus promoting tumor cell proliferation and EMT." (PMID 30149591, 2018). "Although GSK-3β is ubiquitously expressed, the levels of GSK-3β expression vary widely among the various types of cells and tumor tissues." (PMID 29445085, 2018). "To ascertain the role of GSK3β in tumor cell biology, we examined the effect of GSK3β inhibition on survival and proliferation of CRC cells." (PMID 29568361, 2018). "We found phosphorylation of Fas or Gsk3β in viable CD133+ tumor cells from mice treated with SLV peptide, which increased in mice undergoing combined treatment with oxaliplatin and SLV." (PMID 29899829, 2018). "Wnt signalling probably facilitates the phosphorylation of CTNNB1 and APC by GSK3B and is likely to function as a tumor suppressor." (PMID 30447692, 2018). "In contrast, we observed a reduction of GSK-3α and GSK-3β phosphorylation in tumour tissue with respect to normal tissue, which indicates an activation of these enzymes." (PMID 30410539, 2018). "There has been a number of conflicting reports concerning the extent of tumor progression in context with the expression of total GSK3β in human cancers." (PMID 29963225, 2018). "In contrast to the increased DKK3 protein levels in murine tumour tissues, both p‐GSK3β and nuclear β‐catenin expression decreased after MYCN shRNA treatment." (PMID 29673070, 2018). "Our previous study had confirmed that CKD5RAP3 suppressed tumor cells through the inhibition of β-catenin signaling by regulating GSK-3β phosphorylation." (PMID 29540196, 2018). "GSK3B is dysregulated in a variety of tumor tissues including CC19–24, and it participates in the development of CC caused by HPV16 infection by regulating Wnt signaling/β-catenin pathway." (PMID 30275981, 2018). "The mechanistic studies in vivo indicated that ROCK1/PTEN/PI3K/Akt signaling pathway-regulated GSK3β dephosphorylation and apoptosis are involved in hirsutine-inhibited tumor growth in an A549 xenograft mouse model." (PMID 29789524, 2018). "Accumulating evidence has shown that inhibition of GSK3β provides dual benefits for the treatment of GBM patients by attenuation of tumor progression and protection from neurodegenerative effects of irradiation." (PMID 28423558, 2017). "Activation of GSK3β in the tumor inversely correlated with patient survival as an independent prognostic factor." (PMID 28423558, 2017). "Wnt/GSK3β/β-catenin signaling pathway plays an important role in tumorigenesis, tumor progression and cancer therapy." (PMID 29156633, 2017). "Emerging evidence suggests that GSK3β promotes GBM progression by interacting with the pivotal molecules that participate in tumor cell survival, proliferation, invasion, and resistance to chemoradiation therapy." (PMID 28423558, 2017).